PTPRK (protein tyrosine phosphatase receptor type K)
Diseases named in the same sentence as PTPRK in open-access papers (continued):
Sharing a sentence is not in itself a finding about the gene and the disease.
colon cancer (5 papers, 2019 to 2020). "Given that p‐Bad inhibits apoptotic cell death induced by the intrinsic mitochondrial pathway 41, we sought to investigate whether PTPRK could be implicated in CD133‐associated anti‐cancer drug resistance of colon cancer cells." (PMID 30947381, 2019). "Aberrant Wnt/R-spondin/ZNRF3 signaling is implicated in tumorigenesis, where 7% of colon cancer and 31% of serrated adenoma samples harbor RSPO3 gene fusions with the neighboring Protein tyrosine phosphatase receptor-type kappa (PTPRK) gene." (PMID 31934854, 2020). "As expected, the volume of tumors arising from HT‐29/shPTPRK#2 cells was larger than that of HT‐29/pLKO cells, indicating that PTPRK gene silencing contributes to the tumor progression of colon cancer cells." (PMID 30947381, 2019). "In this study, we have demonstrated that knockdown of PTPRK potentiates the pro‐oncogenic CD133–AKT pathway in colon cancer cells." (PMID 30947381, 2019). "Together, these observations suggest that PTPRK suppresses CD133‐mediated colon cancer growth both in vitro and in vivo." (PMID 30947381, 2019). "Their mechanism of action has been reported as the downregulation of protein tyrosine phosphatase receptor type K (PTPRK) in vitro, since PTPRK is a tumor suppressor gene product that may be involved in colon cancer." (PMID 33371188, 2020). "Thus, this is suggestive that forced depletion of PTPRK contributes to the aggressive properties of CD133‐positive colon cancer cells through the potentiation of the pro‐oncogenic CD133–AKT pathway." (PMID 30947381, 2019). "Other evidence suggested that PTPRK was a potential tumor suppressor in colon cancers." (PMID 30838170, 2019). "To address whether PTPRK could attenuate the aggressive growth of colon cancer cells through the inhibition of CD133, we have employed CD133‐negative human colon cancer SW480 cells." (PMID 30947381, 2019). "Previous studies have shown that defects in Wnt signaling and in the activities of PTPRK and ZNRF3 are involved in colon cancer in mammals." (PMID 31934854, 2020). "For this purpose, non‐depleted and PTPRK‐depleted SW480/CD133 cells were treated with the indicated concentrations of oxaliplatin, which is commonly used in a standard chemotherapy for colon cancer patients." (PMID 30947381, 2019). "In the present study, we have found for the first time that shRNA‐mediated knockdown of PTPRK significantly augments tumor growth and markedly reduces the anti‐cancer drug oxaliplatin sensitivity of CD133‐expressing colon cancer cells." (PMID 30947381, 2019). "PTPRK dephosphorylates CD133, which is a stem cell marker; phosphorylated CD133 accelerates xenograft tumor growth of colon cancer cells through the activation of AKT, but the functional significance of this has remained elusive." (PMID 30947381, 2019).
colorectal cancer (5 papers, 2015 to 2024). A primary or metastatic malignant neoplasm that affects the colon or rectum. "Truncating variants and a PTPRK-inactivating gene fusion with the Wnt potentiator RSPO3 are also found in human colorectal cancers." (PMID 38904097, 2024). "PTPRK is also a transforming growth factor β1 (TGFβ1) target gene in mammary epithelial cells, synoviocytes and keratinocytes, and has been implicated as a tumour suppressor in several cancer types, particularly colorectal cancer." (PMID 38904097, 2024). "Therefore, overexpression of RSPO3 and loss of PTPRK could confer a double hit in colorectal cancer (CRC) harboring the RSPO3-PTPRK fusion." (PMID 34585724, 2021). "HT29 cells have the highest mRNA levels of wild-type (WT), processed PTPRK amongst commonly used cultured colorectal cancer cell lines." (PMID 38904097, 2024). "Here, we find that PTPRK regulates cell adhesion signalling, suppresses invasion and promotes collective, directed migration in colorectal cancer cells." (PMID 38904097, 2024). "Here, we set out to understand PTPRK function in the mouse colon and in human colorectal cancer cells." (PMID 38904097, 2024). "Translocations where the signal sequence or part of the extracellular domain of PTPRK is fused to RSPO3 are recurrent events in a subset of colorectal cancers." (PMID 31934854, 2020). "Thus, we have established cell lines to assess the impact of PTPRK and its phosphatase activity on colorectal cancer cell behaviours." (PMID 38904097, 2024). "Thus, deleting PTPRK from colorectal cancer cells leads to altered adhesive signalling and morphological changes resembling a more mesenchymal state, similar to previous findings in MCF10A cells." (PMID 38904097, 2024). "In addition, we confirm that PTPRK functions as a tumour suppressor in the mouse colon and in colorectal cancer xenografts." (PMID 38904097, 2024). "To study PTPRK function, we used CRISPR/Cas9 editing to delete it from HT29 and DLD1 human colorectal cancer cells." (PMID 38904097, 2024). "To test PTPRK tumour suppressor function directly in mice, we implemented the azoxymethane (AOM)–DSS colorectal cancer model." (PMID 38904097, 2024). "PTPRK is a candidate tumor suppressor in mouse intestinal tumorigenesis as per insertional mutagenesis, and is a gene fusion partner with the oncogene RSPO3 in colorectal cancers." (PMID 31934854, 2020).
ovarian carcinoma (5 papers, 2019 to 2025). A malignant neoplasm originating from the surface ovarian epithelium. "We have proved the loss of PTPRK expression in ovarian cancer cell lines resistant to six different cytotoxic drugs." (PMID 31027318, 2019). "Previously, we observed downregulation of PTPRK in fifteen ovarian cancer cell lines and restoration of its expression by piperine treatment correlated with increased sensitivity to PAC." (PMID 41465532, 2025). "Previously, we reported a downregulation of PTPRK expression in 15 drug-resistant ovarian cancer cell lines derived from W1 and A2780 ovarian cancer cell lines." (PMID 33921897, 2021). "We recently observed reduced expression of PTPRK and increased level of total tyrosine phosphorylation in fifteen drug resistant ovarian cancer cell lines." (PMID 33921897, 2021). "The present study aimed to examine the expression of PTPRK in ovarian cancer cell lines resistant to: CIS, PAC, DOX, TOP, VIN, and MTX and the impact of this molecule expression on total phosphotyrosine (pTYR) level and drug resistance." (PMID 31027318, 2019). "The microarray data obtained before have suggested that changes in PTPRK gene expression can be involved in drug resistance in ovarian cancer." (PMID 31027318, 2019). "The research has found decreased level of PTPRK expression in ovarian cancer cell lines resistant to CIS, PAC, DOX, TOP, VIN and MTX." (PMID 31027318, 2019). "The second goal of this paper is to compare the relations between ALDH1A1 and PTPRK expression in development of drug resistance in ovarian cancer cell lines." (PMID 31027318, 2019). "Expression of PTPRK in ovarian cancer suggests its involvement in cancer progression; however, to further explain the significance of PTPRK in tumor development, a big cohort of patients should be analyzed." (PMID 31027318, 2019). "Distinct types of ovarian cancer were immunohistochemically analysed in regard to verifying tissue expression of PTPRK." (PMID 31027318, 2019). "Several cases of different ovarian cancer subtypes were tested and all of them showed positive signal for PTPRK expression." (PMID 31027318, 2019). "In summary, according to our knowledge, the presented study is the first report about PTPRK expression in drug resistant cell lines and in ovarian cancer tissue." (PMID 31027318, 2019). "Previously, we observed reduced expression of PTPRK in 17 drug-resistant ovarian cancer cell lines." (PMID 35008952, 2022). "The results of the present study may improve our understanding of PTPRK in mechanisms leading to drug resistance in ovarian cancer." (PMID 31027318, 2019). "The final step of our research was to examine PTPRK expression in ovarian cancer tissue." (PMID 31027318, 2019). "However, the significance of PTPRK expression downregulation in drug resistant cell lines and in ovarian cancer development requires further investigation and should be confirmed in ovarian cancer cell lines developed from different histological types of cancer, and for a larger group of patients." (PMID 31027318, 2019). "A positive expression of PTPRK protein was observed regardless of the type of ovarian cancer." (PMID 31027318, 2019).
type 1 diabetes (4 papers, 2018 to 2024). "We recently mapped a genetic susceptibility locus on chromosome 6q22.33 for type 1 diabetes (T1D) diagnosed below the age of 7 years between the PTPRK and thymocyte-selection-associated (THEMIS) genes." (PMID 35986039, 2022). "We performed fine-mapping across the 6q22.33 region, which contains the adjacent PTPRK and THEMIS genes, and has never previously been associated with AAD or type 1 diabetes, but has been reported to be associated with susceptibility to other autoimmune diseases." (PMID 28983737, 2018).
Hodgkins lymphoma (3 papers, 2013 to 2021). A heterogeneous group of malignant lymphoid neoplasms of B-cell origin characterized histologically by the presence of Hodgkin and Reed-Sternberg (HRS) cells in the vast majority of cases. "At the same time, EBNA1 can promote the degradation of Smad2 protein and inhibit the transcription of TGF-β target gene protein tyrosine phosphatase receptor κ (PTPRK), thereby promoting the growth and survival of Hodgkin lymphoma (HL) cells." (PMID 33549103, 2021). "When PTPRK is over-expressed in EBV-infected Hodgkin lymphoma cells, survival of these cells decreases; when PTPRK expression is knocked down by RNAi, survival increases; suggesting a role for PTPRK in tumour suppression." (PMID 25290448, 2014). "A study using Hodgkin’s Lymphoma cells likewise found a reduced half-life of SMAD2 and found also the level of the TGFβ1 responsive gene, Protein Tyrosine Phosphotase Receptor K (PTPRK), was reduced in EBNA1’s presence." (PMID 23325328, 2013).
acute lymphoblastic leukemia (2 papers, 2019 to 2021). Leukemia with an acute onset, characterized by the presence of lymphoblasts in the bone marrow and the peripheral blood. "PTPRK promoter methylation in acute lymphoblastic leukemia (ALL) also correlated with decreased overall survival and restoration of PTPRK expression resulted in reduced cells proliferation in Raji cell line." (PMID 31027318, 2019). "The acute lymphoblastic leukemia (ALL) cell lines Raji and Jurkat transfected with PTPRK vector were significantly more sensitive to AraC than cells transfected with empty vector." (PMID 31027318, 2019).
central nervous system lymphomas (2 papers, 2012 to 2019). "In primary central nervous system lymphomas (PCNSL), a tendency toward higher mortality was observed among patients with a loss of PTPRK expression." (PMID 31027318, 2019). "Additionally, a tumour suppressor function has been indicated for PTPκ (PTPRK) in primary central nervous system lymphomas, and PTPδ (PTPRD) in laryngeal squamous cell carcinoma and other human cancers." (PMID 23185569, 2012).
inflammatory bowel disease (2 papers, 2019 to 2024). A spectrum of small and large bowel inflammatory diseases of unknown etiology. "Furthermore, single nucleotide polymorphisms (SNPs) within the PTPRK genic region are associated with inflammatory bowel diseases (IBDs) and type I diabetes age of onset." (PMID 30924770, 2019).
lung carcinoma (2 papers, 2017 to 2019). "Collectively, our results validated the PTPRK-mediated tumor suppressor functions by inhibiting proliferation and metastasis of lung cancer cells." (PMID 30838170, 2019). "Although some studies have shown that the expression of PTPRK was significantly downregulated in lung cancer-derived cell lines, its contribution to aberrant signaling in lung cancers remains largely unexploited." (PMID 30838170, 2019). "After reducing PTPRK expression in vitro, we observed the strongly promoted capabilities of cell proliferation, invasiveness, and migration, as expected for a tumor suppressor in lung cancer." (PMID 30838170, 2019). "Therefore, the decreasing activity of PTPRK may be partly accountable for the constitutive activation of STAT3 in lung cancers." (PMID 30838170, 2019). "Therefore, we explored whether the downregulation of PTPRK leads to STAT3 activation in lung cancers." (PMID 30838170, 2019). "It hinted towards a negative role of PTPRK in lung cancer invasion and metastasis, which is consistent with its function in other cancers." (PMID 30838170, 2019).
malignant glioma (2 papers, 2013 to 2017). A grade III or grade IV glioma arising from the central nervous system. "Overall, the data indicate that mutations and deletions of the PTPRK gene alter its suppressive effect on the invasive phenotypes of malignant glioma." (PMID 23696788, 2013). "PTPRK mutations were cloned and expressed in PTPRK-null malignant glioma cells." (PMID 23696788, 2013). "Our data provide first time evidence in support of PTPRK's major role in checking migratory and invasive phenotype of malignant glioma." (PMID 23696788, 2013). "In our previous study, we observed frequent and significant alterations of the PTPRK locus in patients with malignant glioma." (PMID 23696788, 2013). "This possibly suggests that apart from catalyzing dephosphorylation of EGFR and β-catenin, PTPRK also regulates their protein expression in malignant glioma by interacting directly with transcription or by negative feedback-loop after dephosphorylation of EGFR and β-catenin." (PMID 23696788, 2013).
schizophrenia (2 papers, 2021 to 2025). A major psychotic disorder characterized by abnormalities in the perception or expression of reality. "Two differentially expressed genes associated with schizophrenia, RGS6 and PTPRK, are detected within the exc-a subcluster and are recognized as high-confidence susceptibility genes for schizophrenia." (PMID 39397771, 2025). "Possibly, new genes (RGS6 and PTPRK) have been identified in an excitatory neuronal subpopulation that might be important in the pathophysiology of schizophrenia." (PMID 39397771, 2025).
Atrophy (1 paper, 2022). Any weakening or degeneration, especially through lack of use. "In CeD biopsies, both GCD–CeD and Pot–CeD patients the levels of PTPRK that decreased in respect to controls, indicating that the reduction inthe PTPRK protein was independent from the intestinal atrophy." (PMID 36611909, 2022).
Autoimmunity (1 paper, 2018). The occurrence of an immune reaction against the organism's own cells or tissues. "PTPRK and its neighbour THEMIS are required for early development of the thymus, which we can assume influences the initiation of autoimmunity." (PMID 28983737, 2018).
colitis (1 paper, 2024). Inflammation of the colon. "We therefore make the assumption that the DSS colitis model predominantly assesses the impact of PTPRK loss on epithelial barrier integrity and/or repair capacity." (PMID 38904097, 2024). "In vivo, PTPRK supports recovery from inflammation-induced colitis." (PMID 38904097, 2024). "To determine whether PTPRK could regulate the immune response to the DSS colitis challenge, we explored its function in T lymphocytes." (PMID 38904097, 2024). "We found that PTPRK suppresses invasion, promotes collective migration and supports repair following dextran sulphate sodium (DSS)-induced colitis." (PMID 38904097, 2024). "Therefore, to test the in vivo role of PTPRK, we used the well-established DSS colitis model, which tests the integrity of intestinal immune function and epithelial barrier." (PMID 38904097, 2024). "Ptprk−/− mice showed no obvious phenotypes; however, when they were subjected to colitis, a role of PTPRK in epithelial integrity or repair was revealed." (PMID 38904097, 2024).
disc degeneration (1 paper, 2021). "qRT-PCR results showed that the expression levels of ID1, RAP2C, and PTPRK were all significantly higher in NP tissues of the grade IV disc degeneration and high immunity groups." (PMID 34122424, 2021).
epilepsy (1 paper, 2020). A brain disorder characterized by episodes of abnormally increased neuronal discharge resulting in transient episodes of sensory or motor neurological dysfunction, or psychic dysfunction. "The loci near BMP8A and PTPRK initially showed evidence for pleiotropy, because of their nominal significant association in both ALS and epilepsy GWAS and stronger statistical association in the meta-analysis and sign-independent meta-analysis, respectively." (PMID 32409253, 2020).
gastric cancer (1 paper, 2026). A primary or metastatic malignant neoplasm involving the stomach. "The four prioritized mutations (PTPRK, PIK3CB, LRP1B, and IGF2R) provide new insights into the genetic landscape of gastric cancer and represent promising candidates for the development of targeted therapeutic strategies." (PMID 41696640, 2026).
head and neck squamous cell carcinoma (1 paper, 2019). A squamous cell carcinoma that arises from any of the following anatomic sites: lip and oral cavity, nasal cavity, paranasal sinuses, pharynx, larynx, and salivary glands. "Importantly, we employed AlloDriver to discover an unreported target—human protein tyrosine phosphatase, receptor type K (PTPRK)—in head and neck squamous cell carcinoma (HNSC)." (PMID 31069394, 2019).
hearing loss (1 paper, 2021). "Interestingly, a previous GWAS identified that PTPRK (index rs10499138) is significantly associated with hearing loss." (PMID 33242228, 2021). "We observed that several SNPs in SCARNA16, IQGAP2, PTPRK, GLI3, ADARB2 and NDUFV2, which have been reported to be significantly associated with several other types of hearing loss, were also significantly associated with NIHL in this study (all P values ≤ 0.05)." (PMID 33242228, 2021).
hepatoma (1 paper, 2014). "Our previous work revealed that overexpression of GnT-V gene in human hepatoma cell line SMMC-7721 induced the addition of β1,6 GlcNAc branches to N-glycans of PTPRK and decreased the phosphatase activity of PTPRK, thus activating EGFR signaling." (PMID 24846175, 2014).
Immunodeficiency (1 paper, 2022). Failure of the immune system to protect the body adequately from infection, due to the absence or insufficiency of some component process or substance. "It should be noted, however, that PTPRK is directly upstream of gene THEMIS (thymocyte-expressed molecule involved in selection), and rats that suffer from a co-deletion of both genes display defective T-cell maturation because of T-helper immunodeficiency." (PMID 36755664, 2022).
lung adenocarcinoma (1 paper, 2020). A carcinoma that arises from the lung and is characterized by the presence of malignant glandular epithelial cells. "In the H1703 human lung adenocarcinoma cell line, knockdown of PTPRK enhanced Wnt3a induced signaling in Topflash reporter assays as well as expression of the endogenous Wnt target gene AXIN2." (PMID 31934854, 2020).
lymph node metastasis (1 paper, 2019). "The results showed that PTPRK expression was frequently reduced in NSCLC tissues with lymph node metastasis and cell lines." (PMID 30838170, 2019). "Importantly, the expression of phospho-STAT3Tyr705 was significantly inversely correlated with the mRNA levels of PTPRK in 26 NSCLC tissues (r = −0.727, p < 0.001), and high expression of phospho-STAT3Tyr705 was positive correlated with lymph node metastasis of patients with NSCLC (p = 0.041)." (PMID 30838170, 2019).
metastasis (1 paper, 2019). The spread or migration of cancer cells from one part of the body (where they first appeared) to another. "Moreover, the phospho-STAT3Tyr705 levels of NSCLC tissues were positively correlated with lymph node metastasis and significantly inversely correlated with the expression of PTPRK (p < 0.05)." (PMID 30838170, 2019).